HAVCR1 (hepatitis A virus cellular receptor 1)
Diseases named in the same sentence as HAVCR1 in open-access papers (continued):
Sharing a sentence is not in itself a finding about the gene and the disease.
kidney cancer (6 papers, 2021 to 2026). Primary or metastatic malignant neoplasm involving the kidney. "In conclusion, this prospective study represents the largest plasma proteome analysis in kidney cancer, identifying biomarkers associated with disease onset, with HAVCR1 emerging as a promising biomarker." (PMID 40928391, 2026). "Here, we present the first large-scale prospective evaluation of plasma HAVCR1 in relation to kidney cancer risk." (PMID 40928391, 2026). "The proteomic model significantly improved kidney cancer risk prediction compared to the clinical model (concordance index [C-index]: 0.811 vs. 0.713, P = 0.029), with HAVCR1 alone demonstrating comparable discriminative ability (C-index: 0.754)." (PMID 40928391, 2026). "After Bonferroni correction, HAVCR1 emerged as the most significant plasma protein independently associated with incident kidney cancer (HR = 3.181, 95% CI: 2.704–3.744, P = 3.82 × 10−44)." (PMID 40928391, 2026). "Finally, we focused specifically on the association between pre-diagnostic plasma HAVCR1 levels and incident kidney cancer." (PMID 40928391, 2026). "We also observed associations between 131 proteins and risk of liver cancer that included IGFBP7 and IGFBP3 [1.65 (1.48–1.84) and 0.46 (0.39–0.54), respectively], and 51 proteins and risk of kidney cancer, such as HAVCR1 and ESM1 [2.88 (2.55–3.24) and 1.84 (1.55–2.19)]." (PMID 38750076, 2024). "Importantly, integrating HAVCR1 into the proteomics-driven risk model improved its discriminative performance, emphasizing its value within a comprehensive early detection framework for kidney cancer." (PMID 40928391, 2026). "To deepen our understanding of the relationship between HAVCR1 and kidney cancer, we analyzed protein data from tumor patients in the CPTAC database, revealing significantly higher HAVCR1 expression in tumor tissues compared to adjacent normal tissues." (PMID 40928391, 2026). "This large-scale plasma proteomics study highlights the potential of biomarkers, particularly HAVCR1, for early detection and insight into kidney cancer pathophysiology." (PMID 40928391, 2026). "A prospective nested case-control study also reported that plasma HAVCR1 levels could predict kidney cancer up to 5 years before diagnosis." (PMID 40928391, 2026). "This highlighted HAVCR1 as a particularly promising biomarker for early detection of kidney cancer." (PMID 40928391, 2026). "HAVCR1, a transmembrane glycoprotein shed by kidney cancer cells and detectable in both blood and urine, is among the most extensively studied biomarkers for kidney cancer." (PMID 40928391, 2026). "Consistent with previous research, we observed elevated levels of HAVCR1, MMP7, and ESM1 in kidney cancer patients." (PMID 40928391, 2026). "However, previous research had not explored the temporal dynamics of HAVCR1 in relation to kidney cancer development." (PMID 40928391, 2026).
malaria (6 papers, 2015 to 2025). Malaria is a serious and sometimes fatal disease caused by a parasite that commonly infects a certain type of mosquito which feeds on humans. "These genes include inflammatory responding genes, such as NFκB and CXCL1, parasite protein receptors, such as BSG and PROCR, and the genes involving protection against malaria, such as HLA-B and HAVCR1." (PMID 26099491, 2015).
Autoimmunity (5 papers, 2018 to 2025). The occurrence of an immune reaction against the organism's own cells or tissues. "Another study detected that mice deficient for TIMD4 or HAVCR1 have increased susceptibility for autoimmunity, as shown by hyperactive T- and B-cell responses in TIMD4−/− mice and increased Th2 responses in HAVCR1−/− mice." (PMID 29208769, 2018). "The role of the HAVCR1 156ins/delPMTTTV polymorphisms in autoimmunity has been more difficult to assess due to the nonrandom association with other polymorphisms in HAVCR1." (PMID 39595207, 2024). "HAVCR1 is expressed in several cell types including hepatocytes, tubular epithelial kidney cells, mast cells, and lymphoid cells, playing an important role in the regulation of allergy, autoimmunity, infectious diseases, graft versus host disease, and cancer." (PMID 39595207, 2024).
clear cell renal cell carcinoma (5 papers, 2022 to 2025). "In clear cell renal cell carcinoma, there is a known link between the HAVcR-1 ectodomain shedding effect invasiveness and tumour malignancy, and it would, therefore, be interesting to investigate if a similar effect is seen in prostate cancer." (PMID 35204839, 2022). "Amongst the 28,446 tumor-specific pHLAs, we highlighted a highly recurrent, abundant, and tumor-specific HAVCR1-derived peptide in clear cell renal cell carcinoma, an ideal PC-CAR target, providing an alternative strategy to avoid the ectodomain shedding for conventional CAR." (PMID 40672284, 2025).
colorectal cancer (5 papers, 2017 to 2023). A primary or metastatic malignant neoplasm that affects the colon or rectum. "The HAVCR1 gene is a biomarker for diagnosing renal cell, ovarian, and colorectal carcinoma." (PMID 28249600, 2017).
gastric adenocarcinoma (5 papers, 2019 to 2025). "The HAVCR1 gene encodes a type I transmembrane glycoprotein, which is upregulated in various cancers, including esophageal cancer, lung adenocarcinoma, and gastric adenocarcinoma with different pathological characteristics, and its expression is associated with poor prognosis in these cancers." (PMID 40406257, 2025). "Hence, we aimed to detect the effects of HAVCR1 on gastric adenocarcinoma (GAC)." (PMID 31885544, 2019).
hepatitis A (4 papers, 2017 to 2024). "The presence of hepatitis A virus cellular receptor 1 (HAVCR1) is intriguing, although it may protect against atopy when hepatitis A virus infection rates were high." (PMID 28598986, 2017). "Long-HAVCR1, which binds HAV more efficiently than short-HAVCR1, was associated with increased severity of hepatitis A in Argentinean but not in Indian children." (PMID 39595207, 2024). "Further, the lipid receptors hepatitis A virus cellular receptor 1 (HAVCR1) and NPC intracellular cholesterol transporter 1 (NPC1) were found to be required for endosomal fusion and cargo delivery, and HAVCR1 was shown to serve as a receptor for hepatitis A EVs and mediate infection." (PMID 39811728, 2024).
ovarian clear cell cancer (4 papers, 2019 to 2025). An invasive malignant neoplasm that arises from the ovary and is characterized by a predominance of clear and hobnail malignant epithelial cells. "HAVCR1 serves as the marker for ovarian clear cell carcinoma susceptibility." (PMID 34950205, 2021).
Atrophy (3 papers, 2017 to 2025). Any weakening or degeneration, especially through lack of use. "For biomarkers of kidney injury, while both models had decreases in Havcr1 expression 1 day after IRI, the decrease was significantly slower for the atrophy model." (PMID 36951957, 2023).
colon cancer (3 papers, 2021 to 2025). "Transfection of the colon cancer cells with HAVcr-1 gene does not influence the growth rate and cell motility in vitro but reduces their invasion ability." (PMID 34603757, 2021).
coronary heart disease (3 papers, 2018 to 2024). "Little is known about the association of the TIMD4 (T-cell immunoglobulin and mucin domain 4 gene)-HAVCR1 (hepatitis A virus cellular receptor 1) variants and lipid metabolism, the risk of coronary heart disease (CHD) and ischemic stroke (IS)." (PMID 29208769, 2018).
dyslipidemia (3 papers, 2023 to 2025). "Meta-analyses of the European ancestry genome-wide association study (GWAS) suggested that variants of rs3846663 in HMGCR, rs1501908 between TIMD4 and HAVCR1, rs2650000 near HNF1A, and rs6102059 near MAFB were associated with dyslipidemia." (PMID 37334397, 2023).
hepatocellular carcinoma (3 papers, 2013 to 2023). A malignant tumor that arises from hepatocytes. "Previous research has also revealed that HAVCR1 was overexpressed in hepatocellular carcinoma and pancreatic adenocarcinoma and is possibly a marker for cancer." (PMID 37296766, 2023). "Hepatocellular carcinoma cells (Huh7, and HepG2) proliferation, motility, and invasion were all remarkably inhibited by HAVCR1 siRNA." (PMID 35982956, 2022).
metastatic disease (2 papers, 2022 to 2025). "These potential signalling pathways and further studies on inhibitors to HAVcR-1-induced cell behavioural changes and the signalling pathways activity are required to potentiate the HAVcR-1 inhibition as a treatment of prostate cancer and/or prevention of metastatic disease." (PMID 35204839, 2022).
pancreatic adenocarcinoma (2 papers, 2022 to 2023). "Overall, our findings suggest that HAVCR1 upregulation is associated with a high risk for Liver hepatocellular carcinoma and Pancreatic adenocarcinoma and correlates with poor survival." (PMID 35754803, 2022). "Notably, HAVCR1 was associated with immune cell infiltration in Liver hepatocellular carcinoma and Pancreatic adenocarcinoma." (PMID 35754803, 2022). "Overall, we provided compelling evidence that HAVCR1 could be a prognostic and diagnostic marker for Liver hepatocellular carcinoma and Pancreatic adenocarcinoma." (PMID 35754803, 2022). "In this study, we assessed the role of the promoter methylation level of HAVCR1 as a biomarker for early tumor detection and their potential clinical applications in Liver hepatocellular carcinoma and Pancreatic adenocarcinoma." (PMID 35754803, 2022). "In Liver hepatocellular carcinoma and Pancreatic adenocarcinoma, high HAVCR1 expression correlated with immune cell infiltration." (PMID 35754803, 2022). "In the present study, we found that the promoter methylation of HAVCR1 was decreased in Liver hepatocellular carcinoma and Pancreatic adenocarcinoma." (PMID 35754803, 2022). "During Kaplan-Meier analysis, high HAVCR1 expression in Liver hepatocellular carcinoma and Pancreatic adenocarcinoma correlated with poor survival." (PMID 35754803, 2022). "HAVCR1 was associated with increased infiltration of B cells, CD8 cells, macrophages, neutrophils and Dendritic cells in Liver hepatocellular carcinoma and Pancreatic adenocarcinoma." (PMID 35754803, 2022). "HAVCR1 expression was positively correlated with the immune, stromal and estimate scores of Pancreatic adenocarcinoma and the stromal and estimate scores of Liver hepatocellular carcinoma." (PMID 35754803, 2022). "High expression of HAVCR1 correlated with a worse prognosis in Liver hepatocellular carcinoma (HR = 1.74, 95% CI: 1.14–2.67, and p = 0.0093) and Pancreatic adenocarcinoma (HR = 2.01, 95% CI: 1.31–3.07, and p = 0.0011)." (PMID 35754803, 2022). "Herein, we sought to explore the function of HAVCR1 in tumors, especially in Liver hepatocellular carcinoma and Pancreatic adenocarcinoma." (PMID 35754803, 2022). "We found that overexpression of HAVCR1 correlated with the stromal score, immune score and estimate score in Liver hepatocellular carcinoma and Pancreatic adenocarcinoma." (PMID 35754803, 2022). "The ROC curves revealed that the AUCs of HAVCR1 for predicting the 5-years survival of Liver hepatocellular carcinoma and Pancreatic adenocarcinoma patients were 0.738 and 0.619, respectively." (PMID 35754803, 2022). "Our results showed that HAVCR1 was overexpressed while the promoter methylation of HAVCR1 was decreased in Liver hepatocellular carcinoma and Pancreatic adenocarcinoma." (PMID 35754803, 2022). "We found that HAVCR1 was associated with HHLA2, CD44 and TNFRSF4 in Liver hepatocellular carcinoma and Pancreatic adenocarcinoma." (PMID 35754803, 2022). "Given the poor prognostic role of HAVCR1 in various tumor types, we focused on the role of HAVCR1 in Liver hepatocellular carcinoma (p < 0.01) and Pancreatic adenocarcinoma (p < 0.001)." (PMID 35754803, 2022). "We found that the promoter methylation level of HAVCR1 was significantly downregulated in Liver hepatocellular carcinoma and Pancreatic adenocarcinoma, which might lead to HAVCR1 overexpression." (PMID 35754803, 2022). "Importantly, HAVCR1 has huge prospects as a potential target of immune checkpoint blockade therapy in Liver hepatocellular carcinoma and Pancreatic adenocarcinoma patients." (PMID 35754803, 2022). "Moreover, HAVCR1 was upregulated in stage 2 (p < 0.001) and stage 3 (p < 0.05) compared to normal tissue in Pancreatic adenocarcinoma patients." (PMID 35754803, 2022).
pancreatic adenocarcinoma (continued). "Furthermore, HAVCR1 expression was correlated with other immune molecules such as HHLA2 (Human endogenous retrovirus-H long terminal repeat-associating protein 2), CD44 and TNFRSF4 (TNF Receptor Superfamily Member 4) in Liver hepatocellular carcinoma and Pancreatic adenocarcinoma." (PMID 35754803, 2022).
prostate carcinoma (2 papers, 2019 to 2022). A carcinoma that arises from epithelial cells of the prostate gland. "This study aims to investigate the expression of HAVcR-1 in prostate cancer samples and the exploration of the cellular/molecular impact of HAVcR-1." (PMID 35204839, 2022). "This study showed that serum levels of the HAVcR-1 ectodomain varied in prostate cancer and, therefore, identified a novel area of study in prostate cancer diagnosis and monitoring." (PMID 35204839, 2022). "This study also aimed to assess the total HAVcR-1 expression in prostate cancer, which revealed a significant increase in HAVcR-1 protein expression in prostate cancer tissue samples in comparison to normal control samples." (PMID 35204839, 2022). "We also set out to evaluate the effect of HAVcR-1 on prostate cancer cell behaviours that were imperative for metastasis to occur." (PMID 35204839, 2022). "The manipulation of HAVcR-1 levels within prostate cancer cell lines determined changes in cell behaviour using in vitro cell models and barrier function assays." (PMID 35204839, 2022). "Two possible explanations for this are that either the cleavage event that resulted in the release of the ectodomain was decreased in prostate cancer or there was a decreased entry of the HAVcR-1 ectodomain into the circulation in prostate cancer." (PMID 35204839, 2022). "A decreased cellular cleavage appears unlikely due to previously documented increased urinary HAVcR-1 levels with the occurrence of prostate cancer." (PMID 35204839, 2022). "Histologically, the total protein/gene expression of HAVcR-1 was overexpressed in prostate cancer." (PMID 35204839, 2022). "Therefore, a similar trend was seen in cell lines as in the clinical samples, that HAVcR-1 is overexpressed at the protein and gene level in prostate cancer." (PMID 35204839, 2022). "Serum HAVcR-1 ectodomain levels in prostate cancer: To investigate the release of the HAVcR-1 ectodomain into the circulation during the occurrence of prostate cancer, HAVcR-1 ectodomain levels were assessed in serum samples from patients with prostate cancer and from healthy controls using ELISA." (PMID 35204839, 2022). "Future studies could assess the potential benefits of using serum levels in blood tests in a clinical setting, as well as evaluating the variations in signalling pathways, resulting in the release of HAVcR-1 from prostate cancer cells." (PMID 35204839, 2022). "Cell line expression, therefore, agreed with the clinical data to a suitable degree that they could be used for further study into the effect of HAVcR-1 in prostate cancer." (PMID 35204839, 2022). "Furthermore, using GEO datasets, HAVcR-1 overexpression in prostate cancer was also shown at the gene level." (PMID 35204839, 2022). "Decreased occludin staining in PC-3 HAVcR-1EXP and increased staining in PC-3 HAVcR-1KD suggests that the overexpression of HAVcR-1 would decrease TJ integrity and that targeting HAVcR-1 could, therefore, be a potential therapeutic target for prostate cancer." (PMID 35204839, 2022). "It is also important to note that these are preliminary results and further testing is required prior to HAVcR-1 being used in this capacity, including greater sample numbers and trials to investigate whether serum HAVcR-1 levels can accurately diagnose prostate cancer as well as stage the disease." (PMID 35204839, 2022). "From these data, we concluded that the overexpression of HAVcR-1 in non-aggressive prostate cancer cells led to the acquirement of an invasive phenotype." (PMID 35204839, 2022). "The role of HAVcR-1 in cancer development and progression is an active area of research; however, the role of HAVcR-1 in prostate cancer has not been fully investigated." (PMID 35204839, 2022).
prostate carcinoma (continued). "Moreover, there was no change in HAVcR-1 ectodomain levels found in cell media between cell lines; thus, conferring with the clinical data theory that the variation in serum HAVcR-1 ectodomain levels with the occurrence of prostate cancer is not due to a variation in the amount of HAVcR-1 cleavage." (PMID 35204839, 2022).
Acute hepatitis (1 paper, 2009). Acute hepatic injury resulting from inflammation typically accompanied by increased serum alanine transaminase activity. "Hepatitis A virus (HAV), an atypical Picornaviridae that causes acute hepatitis in humans, usurps the HAV cellular receptor 1 (HAVCR1) to infect cells." (PMID 19860892, 2009).
Crohn disease (1 paper, 2024). A gastrointestinal disorder characterized by chronic inflammation involving all layers of the intestinal wall, noncaseating granulomas affecting the intestinal wall and regional lymph nodes, and transmural fibrosis. "Genes in CD4+ T cells with a negative t value for association with the PRS included HAVCR1 in Crohn’s disease." (PMID 38590520, 2024).
HIV-1 infection (1 paper, 2024). The type species of lentivirus and the etiologic agent of acquired immunodeficiency syndrome (AIDS). "CD4+ T cells that express short-HAVCR1 have a lower rate of HIV-1 infection in vitro that was associated with protection from HIV-1 infection in exposed seronegative individuals." (PMID 39595207, 2024).
lymph node metastasis (1 paper, 2025). "The concordance statistic, net reclassification improvement, and integrated discrimination improvement values for predicting lymph node metastasis by immunohistochemical scores of HAVCR1." (PMID 40406257, 2025).
prostate tumour (1 paper, 2022). "The GSE6919 GEO dataset was used to assess for differences in HAVcR-1 gene expression between normal prostate tissue free of any pathological alteration (n = 18) and primary prostate tumour samples (n = 65)." (PMID 35204839, 2022).
kidney disease (141 papers, 2011 to 2026). "Cluster 1, featuring HAVCR1, was associated with membrane invagination and kidney disease." (PMID 40928391, 2026). "HAVCR1 was rebranded as kidney injury 1 (KIM1) because of its role in kidney disease and T-cell immunoglobulin mucin 1 (TIM1) because of its role as a co-stimulatory molecules of T cells." (PMID 39595207, 2024). "Mori ever reported HAVCR1 could mediate FA uptake to promote progress of kidney disease." (PMID 35982956, 2022).
kidney (49 papers, 2011 to 2026). "Lrp2 KO mice had significantly increased transcript levels of acute kidney injury markers, kidney injury molecule-1 (KIM-1; Havcr1), and neutrophil gelatinase-associated lipocalin (NGAL; Lcn2), compared with control mice." (PMID 38984983, 2024). "The upregulated genes included known acute kidney injury markers such as Havcr1 (Kim1), S100a6, Clusterin, Cdkn1a, and Spp127–29." (PMID 37898693, 2023). "The T cell immunoglobulin and mucin domain 1 (Tim-1), also known as hepatitis A virus cellular receptor 1 (Havcr-1) and kidney injury molecule 1 (Kim-1), has been shown to affect innate immunity-driven proinflammatory cascade in liver ischemia-reperfusion injury." (PMID 34675931, 2021).